CD163 (CD163 molecule)
Diseases named in the same sentence as CD163 in open-access papers (continued):
Sharing a sentence is not in itself a finding about the gene and the disease.
glioma (continued). "We examined the infiltration of immune cells, particularly CD163+ TAMs, MCs, CD3+ and CD8+ T cells, and found significant infiltration of TAMs and MCs to high-grade gliomas whereas CD3+ and CD8+ T cell infiltration was selective and not widespread." (PMID 28445977, 2017). "The proportions of CD163+ macrophages among CD68+ reflect the proportion of macrophages polarized to M2 phenotype, which was correlated with the histological grade in gliomas, and these findings were in accordance with our present study." (PMID 24883329, 2014). "Both the extent of M-CSF production and CD163+ and CD204+ expression on microglia were correlated with glioma grade." (PMID 23983766, 2013). "We also validated the co-expression of CD163 and RBM47 in glioma samples using immunofluorescence." (PMID 39757245, 2025). "CD163 is more highly expressed in glioblastoma tissue than in normal brains or low-grade gliomas (LGGs)." (PMID 40361384, 2025). "Polychromatic immunofluorescence revealed that SIRPB1 co-localizes with TMEM119 (microglia marker), CD86 (M1 macrophage marker), and CD163 (M2 macrophage marker) indicating that SIRPB1 is predominantly found in TAMs, which in glioma tissues exhibit both M1 and M2 characteristics." (PMID 38594692, 2024). "In addition, flow cytometry analysis presented that when cocultured with DHX9‐overexpressed glioma cells, the ratio of CD68+/CD163+ cells were significantly higher than the control." (PMID 36377508, 2023). "Flow cytometry analysis presented that when cocultured with si‐DHX9 glioma cells, the ratio of CD68+/CD163+ cells were significantly lower than the control; however, this effect could be partly reversed by cocultured with CSF1 overexpressed glioma cells." (PMID 36377508, 2023). "In addition, the number of Siglec15+ CD163+ cells was higher in WHO grade IV gliomas than in grade II and III gliomas." (PMID 37325664, 2023). "In the present study, the findings showed that M2 macrophage markers CD163 and CSF1R were positively correlated with STEAP3 expression in glioma, suggesting that the function of STEAP3 might be related to the regulation of macrophage M2 polarization." (PMID 37009153, 2023). "The data showed that the mRNA expression levels of CD68, CD163 and SIGLEC15 were higher in tumor tissues than in normal tissues across a broad spectrum of human cancers, including glioma." (PMID 37234161, 2023). "This is consistent with the single-cell analysis data showing that inflammatory effects were observed in CD163 positive (M2-like) macrophages in UVM and CD163 negative (M0 or M1-like) macrophages in glioma." (PMID 35525921, 2022). "CD11c+CD68+CD163+ APCs were the immune population found to be preferentially enriched in gliomas relative to metastases, irrespective of the tumor compartment being considered (edge, P = 0.0311; tumor, P = 0.0003; necrosis, P = 0.0007)." (PMID 35316217, 2022). "Hence, we concluded that CD68+CD163+ M2 macrophages, and CD8+ T cells, were the prepotent infiltrated immune cell types in glioma." (PMID 36524115, 2022). "In glioma tissue, diffuse gliomas with high-expression SYK exhibited high-expression CD163 by IHC." (PMID 35910221, 2022). "Consistently, TGF-β was mainly derived from Tregs, not mainly from CD163+ TAMs in the glioma TME, based on immunofluorescence localization analysis." (PMID 33576874, 2021). "CD163 is also involved in regulating the role of CK2 in glioma stemness by interacting with CK2β, leading to an increase in phosphorylation of AKT, GSK-3β/β-catenin pathway activity, inappropriate cell cycle progression, and glioma proliferation." (PMID 34680478, 2021). "Some researches had studied CD163, P2RY12 and PLAUR as biomarkers in glioma." (PMID 33408717, 2020). "Moreover, from low-grade glioma to GBM tumors contain increasing numbers of macrophages, which represent the M2-type markers CD163 and CD204." (PMID 32823915, 2020).
glioma (continued). "Moreover, it also demonstrated that positive VAP-1/TAM markers co-immunoreactivities yielded poorer prognosis for glioma patients (VAP-1/CD68, p < 0.0001; VAP-1/iNOS, p = 0.0113; VAP-1/CD163, p < 0.0001)." (PMID 32349342, 2020). "The pattern of TAM development in glioma started first with a microglia phenotype (P2RY12+/TMEM119+), then it turned to polarized macrophage (CD163+), and finally converged into M2b macrophages (IL1RN+) with activated expression of strong angiogenesis signaling molecules (VEGFA)." (PMID 34692159, 2020). "The expression of CD163 and LPAR5 protein were lower in normal brain than glioma." (PMID 33408717, 2020). "After adjustment based on glioma purity, MS4A6A remained notably related to the majority of signatures of immune cells, particularly macrophages (GBM: CD68: ρ = 0.623, p < 0.001; LGG: CD68: ρ = 0.805, p < 0.001) and M2 macrophages (GBM: CD163: ρ = 0.591, p < 0.001; LGG: CD163: ρ = 0.750, p < 0.001)." (PMID 36119086, 2022). "However, most glioma cases showed CD68+ macrophage/microglia and CD163+ TAM infiltration." (PMID 32528967, 2020). "The similarly high expression of the pan‐M/M marker Iba1 and CD163 in the very distinct entities of pilocytic astrocytomas of WHO grade I and IDH1R132H‐non‐mutant GBMs, as also shown by others 31, challenges a general M1/M2 concept of M/M polarization in gliomas." (PMID 30506802, 2019). "Furthermore, by qPCR, IHC, and Western blotting, in different pathological grades of glioma tissues, we found a significant increase in the expression levels of M2-type macrophage-specific markers with increasing tumor grade, including CD206, CD163, ARG1, CD115, and IL-10." (PMID 36033495, 2022). "The treatment with CMs from glioma cells resulted in elevated expressions of M2-macrophage markers CD206 and CD163, while showing no significant alterations in the M1-macrophage markers CD80 and CD86." (PMID 38576043, 2024). "Moreover, microglia correlates with poorer survival in GBM when considering CD163+ cells, whereas it does not change prognosis in isocitrate dehydrogenase (IDH)-mutant low grade gliomas." (PMID 34071306, 2021). "Although macrophages were abundant in glioma regions showing prominent SH activity, neither TAMRA-FP hotspots nor TAMRA-FP hotspot clusters originated from cells stained for the macrophage markers CD68, CD163 or CD169." (PMID 32190011, 2020). "Although our data do not demonstrate a direct correlation between the density of CD163+ macrophages and survival, their presence in almost all GBM tumor samples is a further confirmation of the importance of macrophages as a possible target of immunotherapy in high-grade gliomas." (PMID 39594814, 2024).
melanoma (113 papers, 2013 to 2026). A malignant, usually aggressive tumor composed of atypical, neoplastic melanocytes. "In primary melanomas associated with development of cerebral metastasis lower expression levels of CD163 were observed." (PMID 40621453, 2025). "CD163+ TAMs exhibiting an M2 phenotype are associated with poor prognosis in breast cancer, melanoma and other solid tumors." (PMID 39594814, 2024). "The selective depletion of CD163 in mice with melanoma caused a massive recruitment of monocytes, which matured into macrophages capable of recruiting and activating T cells, with a consequent increase in the immune response directed against the tumor." (PMID 39594814, 2024). "CD163+ TAMs are known to be strongly associated with poor outcomes in several human tumour types, including melanoma." (PMID 38903497, 2024). "Contrary to our data, a recent publication presented that CD163+ tumor-associated macrophages in melanoma were positively correlated with deeper Breslow level, advanced stage of the disease, and shorter overall survival." (PMID 39015503, 2024). "High numbers of CD68+ macrophages inside tumor cell nests are linked to recurrence, while a low proportion of CD163+ macrophages in the tumor stroma is related to recurrence and, in initial melanomas, also with poor overall survival." (PMID 39703508, 2024). "CSF1 expression correlated with the abundance of CD8 T cells and CD163 tumor-associated macrophages (TAMs) in melanoma." (PMID 37097499, 2023). "Compared with primary melanoma, elevated IL-34 expression is associated with increased CD163+ (an M2-polarization marker) macrophages in refractory metastatic melanoma." (PMID 36798830, 2023). "Considered altogether, Iba1, CD163, and MAC387 expression was significantly associated with tumor-related death associated with death due to melanoma (p < 0.01 for Iba1 and p < 0.05 for CD163 and MAC387)." (PMID 35937296, 2022). "When we performed the analysis on oral tumors and cutaneous tumors separately, CD163 confirmed its association with metastases and with death for melanoma in the oral group (p < 0.05 and p = 0.001, respectively)." (PMID 35937296, 2022). "Oppositely, in human primary melanoma low amount of CD163-expressing TAMs in tumor stroma was associated with recurrence and poor OS." (PMID 36686729, 2022). "The expression of CD163 has a robust association with worse overall survival in human epithelial tumors and melanoma." (PMID 35937296, 2022). "Here, we confirmed that higher numbers of CD163+ve TAMs are associated with a more invasive melanoma phenotype, as indicated by Breslow thickness." (PMID 34831352, 2021). "Diagnostic tissues collected from melanoma patients were evaluated using immunohistochemistry for CD163, PD-1, and LAG-3 expression." (PMID 32756500, 2020). "To assess the relevance of our observation in patients with melanoma, we performed a retrospective analysis by using a collection of 24 metastatic melanoma biopsies, associating the bcl-2 expression with the M2 marker CD163." (PMID 32269145, 2020). "In conclusion, stromal periostin and the number of CD163+ M2 macrophages are mutually correlated risk factors for a poor outcome in patients with melanoma." (PMID 30621220, 2019). "Better objective response rates were associated with metachronous metastases (P = 0.04), PD-L1 tumour- and/or immune-cell status (P = 0.01), CD163+ histiocytes at advancing edges (P = 0.009) of primary melanomas and NRAS mutation (P = 0.019)." (PMID 29973670, 2018). "Population-specific patterns are also evident, such as increased Angiopoietin-1 (Ang-1) and granulocyte colony-stimulating factor (G-CSF) in US studies, and markedly higher CD163—a macrophage activation marker linked to immune suppression—in Japanese melanoma patients with irAEs." (PMID 40722787, 2025). "In melanoma, the accumulation of CD163+ TAMs is associated with poor outcomes." (PMID 38903497, 2024).
melanoma (continued). "In addition, CD163 macrophages play a central role in immunosuppression and are associated with a poor prognosis in different cancers, including melanoma." (PMID 37176042, 2023). "The higher density of CD163+ve TAMs in thicker pT4 melanomas, in comparison with thinner pT1 melanomas and dermal nevi, might suggest an association between immunosuppression and cancer progression." (PMID 34831352, 2021). "Although the prognostic value of CD163 and PD-1 expression in cutaneous melanoma has been reported, the association between the expression of CD163 and PD-1 in melanoma tissue remains unclear." (PMID 32756500, 2020). "Furthermore, the presence of tumor-associated, anti-inflammatory, CD163-positive macrophages suggests that the implanted melanoma cells can have an influence on the local immunological response, thereby creating a pro-cancerous, immunosuppressive, in vivo-like tumor environment." (PMID 41255880, 2025). "Given that CD163 expression is considered a reliable marker of M2-polarized macrophages—associated with immunosuppressive and tumor-promoting activity—further investigation into the role of these cells in melanoma progression is of significant scientific and clinical interest." (PMID 41007741, 2025). "Notably, CD163+ TAMs are associated with a poor prognosis in human melanoma." (PMID 37526660, 2023). "Notably, CD163+ tumor-associated macrophages (TAMs) in melanoma express both PD1 and PD-L1, and blockade of PD-L1/PD1 signals by anti-PD1 Abs activates TAMs, leading to the production of TAM-activating factors such as sCD163 and chemokines in the serum of melanoma patients." (PMID 36555362, 2022). "Therefore, we immunohistologically examined the expression of stromal periostin and the infiltration of CD163+ M2 macrophages in 94 melanoma samples, and statistically analyzed the associations of these variables with the patients’ histological features, clinical stage, and prognosis." (PMID 30621220, 2019). "This suggests that macrophage infiltration, particularly CD163+ cells, correlates with melanoma progression." (PMID 41007741, 2025). "The annotated FOVs of the tissue samples had enriched sinuses were subjected to analysis, revealing an increase in macrophage markers (CD68 and CD163) within the LN sinuses of melanoma patients." (PMID 41271007, 2025). "In a separate Phase I clinical trial (NCT01346358), LY3022855 induced a tumor-localized reduction in CD68+ and CD163+ macrophage levels in patients with solid tumors, including melanoma, as confirmed by histological analysis of biopsies." (PMID 40918451, 2025). "In an experimental melanoma model resistant to anti-PD-1 immunotherapy, CD163+ TAMs maintain immune suppression, and specific targeting of these TAMs restores anti-tumour T cell responses." (PMID 38903497, 2024). "Our results showed that CD163+ TAMs frequently infiltrated dermal and LN melanoma metastases, where they closely interact with both melanoma tumour and T cells." (PMID 38903497, 2024). "Consistent with the phenotype of CD163+ TAMs in the melanoma TME, moTAMs expressed the genes involved in immune suppression, including CD274 (PD-L1), PDCD1LG2 (PD-L2), and TGFB1." (PMID 38903497, 2024). "In a spontaneous BrafV600E-driven mouse melanoma model, specific depletion of CD163+ macrophages resulted in massive infiltration of activated T cells and significantly suppressed tumor growth." (PMID 39516356, 2024). "An earlier study has reported that M-CSF is produced in human melanoma tumours and elevated in the circulation of patients, and also correlates with the presence of CD163+ cells in the TME." (PMID 38903497, 2024). "In some metastatic melanoma samples, we also observed a subset of CD163+ TAMs in melanoma tumours co-localised with DPP4, FN1, and COX2 proteins." (PMID 38903497, 2024). "Our data demonstrated that proliferating moTAMs generated with IL-3 in combination with M-CSF resemble the CD163+ TAMs found in the melanoma TME." (PMID 38903497, 2024).
melanoma (continued). "CD163 expression has prognostic significance and correlates with lower overall survival in multiple human cancers, including melanoma." (PMID 38903497, 2024). "We therefore sought to examine molecular profiles of CD163+ TAMs in the melanoma TME using multicolour immunofluorescence microscopy, especially their expression of the molecules involved in immune suppression." (PMID 38903497, 2024). "We showed that M-CSF transcripts are abundantly present in the melanoma TME, often closely associated with the CD163+ TAMs." (PMID 38903497, 2024). "CD163+ macrophages have also recently been found to play a role in maintaining suppression in anti-PDL1 resistant melanoma in an experimental setting." (PMID 36745657, 2023). "Immunohistochemical staining showed that LL-37 was expressed on CD163+ macrophages, in addition to melanoma cells, as previous reports suggested." (PMID 36980564, 2023). "Contrastly, ROCK-myosin II activation in melanoma cells can differentiate to CD163+ CD206+ protumorigenic macrophages by monocyte chemotaxis." (PMID 37781036, 2023). "This flavoprotein functions as a cell survival factor found in CD163-positive TAMs and melanoma cells." (PMID 37525217, 2023). "CD163 expression was also higher in melanomas with evidence of metastasis and in tumors from dogs that died because of the tumor." (PMID 35937296, 2022). "Surface expression of CD206, CD16 and CD163 on melanoma-conditioned macrophages was inhibited by the addition of T cells, suggesting relief of immuno-suppressive macrophage activation." (PMID 35265066, 2022). "The BF multiplex IHC staining was performed using different combinations of six immune-cell markers—CD3, CD4, CD8, CD20, CD68 and CD163—and the melanoma cell marker SOX10." (PMID 35954345, 2022). "The mechanism by which the CD163+ TAM subset promotes tumor progression has recently been demonstrated in mouse models of melanoma, where the CD163+ TAMs play a key role in suppressing T-cell-mediated antitumor immunity." (PMID 35418199, 2022). "For example, in a mouse model of melanoma, a CD163 antibody conjugated with a lipid carrier loaded with doxorubicin selectively eliminated CD163+ TAMs, enabling tumor regression." (PMID 35158779, 2022). "A significant increase of CD163+ve TAMs was also observed between deeply invasive (pT4) and thin (pT1) melanomas." (PMID 34831352, 2021). "There was robust infiltration of melanoma with CD11c+ expressing cells (CD11c+ single cells and dual CD11c+CD163+ cells, representing a mean of 10% and 8% of total cells, respectively, that lack pSTAT3 expression, indicating antigen presentation capacity." (PMID 34691054, 2021). "Instead, a larger set of ICH genes identifies melanomas with concordant infiltration of B-cell and T-cell lineages, while CD163+ M2-macrophage infiltration suggesting alternate mechanisms for their recruitment." (PMID 34454518, 2021). "When extending findings with M(IL-4) polarized macrophages to patient melanoma-derived TAMs (which we defined as CD45 + CD3-CD11b + CD163 + cells), we observed again that these three β-glucans enhanced secretion of chemo-attractants." (PMID 32860527, 2021). "IHC staining for CD163, which is a commonly used marker for M2 macrophages, was performed, and the percentage of CD163+ TAMs in melanoma was quantitatively analyzed." (PMID 34912726, 2021). "A positive, statistically significant correlation between 4-HNE and CD163+ve cells was found in samples from dermal and dysplastic nevi and pT1 and pT4 melanomas." (PMID 34831352, 2021). "In order to distinguish fibrohistiocytic tumor from malignant melanoma, immunostaining for CD163 and clusterin, together with melanocytic markers, was used." (PMID 34449584, 2021). "Instead, overexpression of a larger set of immune cell homing genes identifies melanomas with concordant infiltration of B-cell and T-cell lineages, while CD163+ M2-macrophage infiltration suggest alternate mechanisms for their recruitment." (PMID 34454518, 2021).